MYC (MYC proto-oncogene, bHLH transcription factor)
Diseases named in the same sentence as MYC in open-access papers (continued):
Sharing a sentence is not in itself a finding about the gene and the disease.
medulloblastoma (303 papers, 2001 to 2026). A malignant, invasive embryonal neoplasm arising from the cerebellum. "Mutations in CTDNEP1 are significantly enriched in MYC-driven medulloblastomas with poor prognosis, suggesting its potential role in cancer development." (PMID 39930152, 2025). "Treatment with EPZ015666 resulted in downregulation of both PRMT5 and MYC protein expression, suppression of cell growth, and induction of apoptosis in MYC-driven medulloblastoma cells associated with G1/S cell cycle arrest." (PMID 39826691, 2025). "MYC amplification/or overexpression is most common in Group 3 medulloblastoma and is positively associated with poor prognosis." (PMID 39779613, 2025). "Group 3 medulloblastoma, representing about 25% of cases, is characterized by its association with MYC amplification and a high propensity for metastasis at diagnosis." (PMID 40868156, 2025). "For instance, WNT-subgroup medulloblastomas tend to have a favorable prognosis with a high survival rate, while Group 3 tumors, frequently associated with MYC amplification, often exhibit aggressive growth and poorer outcomes." (PMID 40868156, 2025). "MYC/MYCN are the most frequent oncogene amplifications in medulloblastoma (MB) and its primary biomarkers of high-risk (HR) disease." (PMID 39377358, 2025). "Overall, findings suggest that deregulation in protein synthesis downstream of MYC can have an immediate and profound effect by causing additional genetic lesions that cooperate with MYC hyperactivation in cancers including medulloblastoma." (PMID 39779613, 2025). "Metastatic Group 3 medulloblastoma (G3 MB) have been shown in several studies to be very high risk, particularly those harboring MYC amplification." (PMID 40229260, 2025). "CDK8 is critical for various types of cancer, with MYC-driven medulloblastoma being the most sensitive cancer type to the loss of CDK8." (PMID 39574899, 2024). "We and others have demonstrated that MYC-amplified medulloblastoma (MB) cells are susceptible to class I histone deacetylase inhibitor (HDACi) treatment." (PMID 37183219, 2023). "MYC amplification or overexpression is most common in Group 3 medulloblastomas and is positively associated with poor clinical outcomes." (PMID 38136401, 2023). "In medulloblastoma (MB), significance is subtype-dependent and associated with a particularly dismal outcome in MYC-amplified group 3 MBs." (PMID 37173990, 2023). "In conclusion, we demonstrate here an association between YB-1 expression and various aspects of medulloblastoma tumourigenesis, including cell invasion, MYC oncoprotein activity and lipid metabolism." (PMID 36831428, 2023). "The molecular mechanisms underlying MYC overexpression in group 3 medulloblastoma remain to be explored." (PMID 37130865, 2023). "A recent study found that MYC-driven medulloblastomas have the most significantly enriched mutation in CTDNEP1." (PMID 37374122, 2023). "Recently, protein arginine methyltransferase 5 (PRMT5) overexpression has been shown to be associated with tumorigenic MYC functions in cancers, particularly in brain cancers such as glioblastoma and medulloblastoma." (PMID 38136401, 2023). "Here we report that mutations in CTDNEP1, a CTD nuclear-envelope-phosphatase, are the most significantly enriched recurrent alterations in MYC-driven medulloblastomas, and define high-risk subsets with poorer prognosis." (PMID 36765089, 2023). "Group 3 medulloblastomas (MBs) have the worst prognosis amongst the subtypes of MBs and are associated with MYC amplifications." (PMID 36765089, 2023). "In MYC-driven medulloblastoma, onvansertib caused a significant downregulation of MYC-target genes and a substantial decrease in Myc protein abundance." (PMID 36902175, 2023).
medulloblastoma (continued). "Molecularly, Group 3 tumors often have MYC amplification or high MYC expression, and high MYC expression has been reported to be an independent risk factor for poor outcome in medulloblastoma." (PMID 35745584, 2022). "The BET inhibitor JQ1 potently decreases cell viability of MYC-amplified medulloblastoma cell lines, causes G1 arrest and apoptosis, and downregulates MYC-targets, as well as MYC transcription itself." (PMID 35745584, 2022). "Since MYC inhibition has been associated with the suppressed expression of B7-H3 in medulloblastoma cells, the MYC-B7-H3 regulatory axis can play an essential role in regulating angiogenesis." (PMID 33800752, 2021). "In some cases, concomitant inhibition of both CHK1 and ATR improves therapeutic efficacy as in high-risk medulloblastomas, where high MYC levels were associated with hypersensitivity to pharmacological inhibition of either CHK1 or ATR." (PMID 34201047, 2021). "Molecular analyses of primary medulloblastoma have also demonstrated WEE1 overexpression alongside amplification of the MYC family of protooncogenes (MYC or MYCN), which characterize high risk disease in patients from SHH, Group 3, and Group 4 sub-groups." (PMID 34277419, 2021). "Five-year overall survival rates for medulloblastoma range from 40 to 98%, depending on molecular subtype, with MYC-amplified Group 3 medulloblastoma associated with very poor survival rates." (PMID 33996894, 2021). "Group 3 medulloblastoma are associated with MYC amplification (10–17%) and the worst overall survival." (PMID 34552068, 2021). "MYC amplification (MYC amp), however, is well established to play a diagnostic and prognostic role in several other malignancies, including medulloblastoma, chondrosarcoma, and post-radiation cutaneous angiosarcoma, in which it imparts a poor prognosis." (PMID 31932576, 2020). "Despite significant improvements in outcomes and overall survival of medulloblastoma patients with current therapies, patients with high-risk disease, particularly MYC-driven medulloblastomas still face a paucity of effective therapies." (PMID 31694585, 2019). "The minimal improvement in survival of these high-risk medulloblastoma patients identifies a need for novel targeted therapeutic approaches against MYC-driven (high-risk) medulloblastoma." (PMID 31694585, 2019). "MYC amplification or overexpression is common in Group 3 medulloblastoma and is associated with the worst prognosis." (PMID 31694585, 2019). "Our results demonstrated that EPZ015666 significantly inhibits proliferation and survival of MYC-driven medulloblastoma cells associated with G1-S cell cycle arrest." (PMID 31694585, 2019). "Stronger PRMT5 band intensity seemed associated with higher MYC expression in medulloblastoma cell lines." (PMID 31694585, 2019). "Expression and association between PRMT5 and MYC in primary medulloblastoma tumors were investigated using publicly available databases." (PMID 31694585, 2019). "Group 3 tumors are often characterized by elevated MYC expression, account for approximately 25% of medulloblastoma cases, and are associated with the worst overall survival among all subtypes." (PMID 30314361, 2018). "In fact, JQ1 is well known to cause downregulation of c-MYC and has been shown to significantly decrease cell proliferation and preferentially induce apoptosis in medulloblastoma derived cell lines expressing high levels of MYC." (PMID 30333915, 2018). "Alterations in WNT signaling are mainly associated with classic medulloblastoma, whereas MYC or MYCN amplifications are found in large cell/anaplastic variants." (PMID 30314361, 2018). "In medulloblastoma MYC (associated with a poor prognosis) had a positive correlation with FDR <0.05, for both the OTC and ARG2 oncogenic and hallmark gene lists." (PMID 28969007, 2017).
medulloblastoma (continued). "Genomic copy number alteration data, together with clinical studies, identifies c-MYC amplification as an important risk factor associated with the most aggressive forms of medulloblastoma with marked metastatic potential." (PMID 27775567, 2016). "Utilizing high-resolution mass spectrometry, we quantified the tumor proteome of group 3 medulloblastoma cells and demonstrate that high-risk MYC amplified tumors can be segregated based on protein expression patterns." (PMID 25970789, 2015). "While the role of this transcript is unclear in medulloblastoma, it is part of a cluster of related lncRNAs that map to the MYC locus and are implicated in cancer risk." (PMID 26380221, 2015). "It is no surprise that Group 3 tumors are associated with this signature given that c-MYC amplification is a major genetic hallmark of this particular subtype of medulloblastoma." (PMID 24796395, 2014). "Our preclinical data provide evidence to pursue testing BET inhibitors, such as JQ1, as molecular targeted therapeutic options for patients with high-risk medulloblastomas overexpressing MYC or harboring MYC amplifications." (PMID 24231268, 2013). "The important role of the MYC oncogene in high-risk medulloblastoma tumorigenesis makes it a compelling, though until recently undruggable, target for drug development." (PMID 24231268, 2013). "Our aim here was to evaluate the efficacy of JQ1 against preclinical models for high-risk MYC-driven medulloblastoma." (PMID 24231268, 2013). "A previous study demonstrated that downregulation of THBS1 was strongly associated with MYC-driven metastatic phenotype of medulloblastoma." (PMID 23768125, 2013). "MYC is another important oncogene in medulloblastoma pathogenesis and high-level amplifications of the MYC locus are significantly associated with a poor clinical outcome." (PMID 22016811, 2011). "Overall, our results indicate that biological factors associated with 8q gain other than MYC achieve clinical significance in our series of medulloblastoma patients." (PMID 16968546, 2006). "Some MYC-amplified medulloblastomas are associated with abnormal activation of SHH pathways." (PMID 39779613, 2025). "Interestingly, studies by us and others have shown that mTOR signaling is overactivated in Group 3 (MYC-amplified) medulloblastoma, suggesting association between MYC and mTOR in medulloblastoma." (PMID 39779613, 2025). "Importantly, MYC-driven medulloblastoma exhibited the most significant susceptibility to the loss of CDK8 among all cancer types." (PMID 39574899, 2024). "Although the contribution of JPO2 and LEDGF/p75 to medulloblastoma chemoresistance was not explored in these studies, both proteins were implicated as novel modulators of the c-MYC/PI3K/AKT signaling axis involved in medulloblastoma aggressiveness and metastasis." (PMID 39682146, 2024). "Especially notable given its role in very high-risk and treatment-refractory medulloblastoma, was the significant inactivation of the MYC oncoprotein following YB-1 knockdown in the D283 MBGroup3 cell line and medulloblastoma patients with low YB-1 gene expression." (PMID 36831428, 2023). "Mutations in CTDNEP1 have been discovered in MYC-driven medulloblastomas." (PMID 37374122, 2023). "Similarly, overexpressing MYC in medulloblastoma cell lines with low MYC expression led to an associated increase in Aurora B expression." (PMID 33322239, 2020).
medulloblastoma (continued). "Therefore we sought to determine if endoreplication was a requirement for cell loss in MYC overexpressing medulloblastoma." (PMID 25739120, 2015). "Because c-MYC is a key driver of high risk medulloblastoma we first asked whether BRD4 inhibition by JQ1 would alter c-MYC driven signaling in medulloblastoma cells." (PMID 24796395, 2014). "To further investigate the mechanism of JQ1 activity in medulloblastoma we asked whether the G0–G1 arrest we observed was associated with senescence given that tumor cells often undergo senescence upon inhibition of MYC." (PMID 24796395, 2014). "We hypothesized that especially high-risk medulloblastomas, which overexpress MYC, could benefit from BET inhibition." (PMID 24231268, 2013). "Furthermore, downstream targets of MYC oncogene and tumor-promoting microRNAs have also been implicated as drivers of medulloblastoma dissemination." (PMID 23768125, 2013). "Finally, the SIOP-Europe high-risk medulloblastoma trial is using molecular screening to identify appropriate cases for increased-intensity treatments, including MYC/MYCN amplification (excluding MYCN amplified Group 4 MB) and SHH-alpha MB (EudraCT Number: 2018-004250-17)." (PMID 34885207, 2021). "However, the role of PRMT5 and its association with MYC in medulloblastoma are unexplored." (PMID 31694585, 2019). "Most children with medulloblastoma fall within the standard-risk clinical disease group defined by absence of high-risk features (metastatic disease, large-cell/anaplastic histology, and MYC amplification), which includes 50–60% of patients and has a 5-year event-free survival of 75–85%." (PMID 30392813, 2018). "Overexpression of protein arginine methyltransferase 5 (PRMT5) is pivotal in MYC-driven primary medulloblastoma tumors, suggesting PRMT5 as a potential therapeutic target." (PMID 42123761, 2026). "MYC is amplified on extrachromosomal DNA (ecDNA) or homogeneously staining regions (HSRs) in group 3 medulloblastoma (G3-MB), conferring a poor prognosis." (PMID 42018144, 2026). "A distinct hotspot area for macrophages was observed in a single case of MYC-amplified medulloblastoma." (PMID 40303994, 2025). "MYC transcription is regulated by histone acetylation in MYC amplified medulloblastoma patients, and BRD and HDAC inhibitors attenuated tumor growth in xenograft mice." (PMID 40664642, 2025). "This review explores concurrent targeting of MYC and mTOR signaling against MYC-driven medulloblastoma." (PMID 39779613, 2025). "The efficacy of MP1 when targeting MYC-amplified medulloblastoma cell lines produced potent IC50 values below 1 μM." (PMID 41149606, 2025). "Potentiation between inhibitors of BET and CDK was earlier shown in MYC-amplified group 3 medulloblastoma." (PMID 39779613, 2025). "Particularly, in Group 3 medulloblastoma, MYC-driven metabolic alterations support rapid cell division and survival under stress." (PMID 39779613, 2025). "Our studies evaluated the anti-cancer potential of combined inhibition of MYC transcription and mTOR signaling in MYC-amplified medulloblastoma." (PMID 39779613, 2025). "Previous studies in G3 medulloblastoma (G3 MB) demonstrated that Minnelide-induced cell death occurs, in part, through an early reduction of the G3 MB dependency gene, MYC." (PMID 41279843, 2025). "The interaction between MYC and mTOR signaling pathways can create a robust network of resistance to therapy in medulloblastoma." (PMID 39779613, 2025). "A combination of CDK and mTOR inhibitors holds potential for controlling MYC-amplified medulloblastoma." (PMID 39779613, 2025). "The upregulation of glycolysis is particularly pronounced in Group 3 medulloblastomas, known for their aggressive behavior and high MYC amplification, as MYC promotes the expression of glycolytic genes." (PMID 40868156, 2025). "This study also demonstrated the potential of BET inhibitors for the treatment of some MYC-driven medulloblastomas." (PMID 41002991, 2025).
medulloblastoma (continued). "For example, hyperacetylation of genes within the MYC pathway in Group 3 medulloblastoma correlates with their high proliferative capacity and poor prognosis." (PMID 40868156, 2025). "In cancers, including medulloblastoma, MYC genes and their transcripts are specific targets for BET protein inhibitors." (PMID 39779613, 2025). "The prodrug inhibited cell growth and induced apoptosis in human MYC-expressing medulloblastoma cell lines." (PMID 40941984, 2025). "Group 3 (G3) medulloblastoma, commonly characterized by hyperactivation of the MYC oncogene, represents the deadliest subgroup of MB." (PMID 40471378, 2025). "The combination of JQ1 and ribociclib potently repressed MYC expression and prevented the induction of its expression in group 3 MYC-amplified medulloblastoma cells." (PMID 39779613, 2025). "Investigation on selective metabolic inhibitors and personalized treatment strategies will be crucial for overcoming resistance and improving outcomes in Group 3 (MYC-driven) medulloblastoma." (PMID 39779613, 2025). "An aberrant increase in PRMT5 level was detected in myelocytomatosis oncogene (MYC)-driven medulloblastoma cells." (PMID 39826691, 2025). "In MYC-driven medulloblastoma, MP1 similarly suppressed growth through destabilization of MYC protein, but the downstream effects diverged in notable ways." (PMID 41149606, 2025). "Multiple studies, including the MAGIC consortium, HIT2000, and the UK research cohort, have demonstrated that metastatic Group 3 medulloblastoma patients exhibit a poor prognosis, particularly those with MYC amplification." (PMID 40229260, 2025). "More specifically, MYC-driven group 3 medulloblastoma cells have been shown to be highly susceptible to inhibition by HDACs and HDAC2 is highly expressed in group 3 medulloblastomas." (PMID 40862786, 2025). "Panobinostat has also demonstrated an anti-tumor effect when combined with BET inhibitor JQ1 in MYC-driven medulloblastoma cell lines and xenografts." (PMID 40862786, 2025). "MTOR signaling-driven deregulated protein synthesis is widespread in various cancers, including medulloblastoma, which can promote the stabilization of MYC." (PMID 39779613, 2025). "Of these, Group 3 medulloblastoma represents the most aggressive subgroup (with < 60% overall survival) which often exhibits MYC amplification or overexpression (17–20% of cases), metastasis (40–50% of cases), and treatment resistance." (PMID 39779613, 2025). "Onvansertib treatment has been shown to increase radiosensitivity of MYC-driven medulloblastoma in vitro and in vivo." (PMID 40166466, 2025). "Chang and colleagues have recently tested a new long half-life AURKA inhibitor (DBPR728) in MYC-overexpressing medulloblastoma xenografts." (PMID 40862786, 2025). "CTPS1 is elevated in medulloblastoma tumor tissue compared to normal brain and correlates with MYC expression in tumors." (PMID 40471378, 2025). "A drug screen for MYC-driven medulloblastoma (MB) identified histone deacetylase inhibitors (HDACi), which suppress growth in part by inducing expression of the FOXO1 tumor suppressor gene, and further synergize with PI3K inhibitors to suppress MB in vivo." (PMID 40075567, 2025). "HDAC2 is a coactivator of c‐MYC in medulloblastoma by facilitating transcription factor licensing of c‐MYC." (PMID 39119816, 2025). "Synergy between MP1 and TEM was confirmed in NSG mice bearing subcutaneous xenografts of MYC-amplified medulloblastoma HD-MB03 cells." (PMID 41149606, 2025). "Group 3/4 medulloblastoma with MYC, MYCN or PRDM6 alterations have complex subclonal structures, with each subclone having unique properties." (PMID 40335697, 2025). "We generated deep tryptic mass spectrometry data for three MYC-high and three MYC-low medulloblastoma cell lines and queried for peptides to ncORFs using a subgroup-specific FDR of 1%." (PMID 39894899, 2025).